NLRP3 (NLR family pyrin domain containing 3)
Diseases named in the same sentence as NLRP3 in open-access papers (continued):
Sharing a sentence is not in itself a finding about the gene and the disease.
colitis (continued). "Together, our data show that rCT-NAMPT may serve as an effective novel candidate therapeutic for colitis by modulating the NLRP3 inflammasome-mediated immune signaling system." (PMID 36552583, 2022). "In colitis-associated colorectal cancer, the NLRP3 inflammasome acts as a negative modulator of tumorigenesis, because NLRP3-dependent IL-18 production promotes epithelial barrier healing, thereby preventing colorectal cancer progression and metastasis." (PMID 35740272, 2022). "This, in addition to the inhibitory effect of TLR4 on SIRT1 levels and its proven role in ROS production, supports the hypothesis that TLR4/NF-κB/NLRP3 inflammasome signaling is the keystone in the inflammatory events encountered in DSS-induced colitis." (PMID 35631426, 2022). "In conclusion, our study demonstrated that oral administration of SM934 exerted therapeutic effects in experimental colitis induced by TNBS via inhibiting the IECs’ apoptosis and blocking the caspase-1-mediated pyroptosis-associated NLRP3/NF-κB/MAPK signal pathways." (PMID 36120344, 2022). "Drugs block the NLRP3 pathway, reduce IL-1β production, and attenuate colitis." (PMID 36590401, 2022). "However, the detailed mechanism for SBLF-mediated colitis improvement and the NLRP3 inflammasome inhibition was unclear." (PMID 36552376, 2022). "We further explored whether Munronoid I exerted its anti-colitis effect of Munronoid I through suppressing the NLRP3 inflammasome activation and pyroptosis." (PMID 35865528, 2022). "NLRP3 inflammasome plays a critical role in inflammatory response as a major component of innate immunity and is involved in exacerbating the mucosal immune response and intestinal epithelial barrier damage during colitis." (PMID 36009057, 2022). "On the other hand, recent studies indicate that NLRP3 inflammasome plays an essential role in colitis induced by CPT-11, and there is evidence showing that CPT-11 could activate NLRP3 inflammasome and cause inflammation both in vitro and in vivo." (PMID 35712724, 2022). "Meanwhile, ginsenoside Rd (10, 20 and 40 mg/kg) could inhibit the NLRP3 inflammasome through the AMPK/ULK1-autophagy signaling pathway in DSS-induced colitis mice." (PMID 36160392, 2022). "Activation of the NLRP3 inflammasome was observed in aged mice with chronic DSS-induced colitis." (PMID 36232412, 2022). "Therefore, the inhibition of the NLRP3 inflammasome and NLRP3−initiated pyroptosis is a promising therapeutic strategy for the prevention and treatment of the inflamed intestine in colitis." (PMID 36290717, 2022). "Previous studies found that PD might play an important role in the treatment of colitis by inhibiting the expression of pro-inflammatory cytokines and activating the NLRP3 inflammasome." (PMID 35450039, 2022). "This dichotomy of function for NLRP3 in the intestine is also apparent in the chronic inflammatory setting of DSS-induced experimental colitis, in which Nlrp3-/- mice have been reportedly either more sensitive or resistant to intestinal inflammation and tissue damage." (PMID 35299732, 2022). "Although the role of the NLRP3 inflammasome in murine IBD models with NLRP3, ASC, or caspase-1 deficiency remains controversial, inhibitors targeting the NLRP3 inflammasome, such as MCC950, oridonin, and INF39, have anti-inflammatory effects in colitis models." (PMID 35330829, 2022). "Thus, we explored the role of circGMCL1/miR-124-3p/DRAM1 network in colitis from the perspective of autophagy and NLRP3 inflammasome-induced pyroptosis." (PMID 36088391, 2022). "Evelyn Saba and colleagues found that ginsenoside Rg3 (20 mg/kg) could decrease the expression of pro-inflammatory mediators and cytokines including NO, IL-1β, IL-5, IL-13, and TNF-α, and levels of NLRP3 inflammasome in DSS-induced colitis mice." (PMID 36160392, 2022).
colitis (continued). "In this study, we demonstrated that oral administration of surfactin containing Bacillus licheniformis-fermented products (SBLF) alleviates dextran sulfate sodium-induced colitis in mice by reducing inflammatory responses and the NLRP3 inflammasome activation in colon tissue." (PMID 36552376, 2022). "Studies have identified the targets of many natural compounds in regulating the progression of colitis and the activation of the NLRP3 inflammasome, whereas, for some other compounds, the investigation that identifying their intracellular targets is still in progress." (PMID 36090968, 2022). "Collectively, these findings illustrated that BUR could ameliorate DSS-induced colitis by improving intestinal barrier function, reducing apoptosis, inhibiting NLRP3 inflammasome activation, and regulating the gut microbiota." (PMID 36290717, 2022). "Furthermore, some studies have also confirmed that PAE inhibited depressive behavior in rats through the NLRP3 pathway and treated colitis by reducing the content of proinflammatory cytokines in the intestine." (PMID 35204061, 2022). "Diverse factors might account for these discrepancies, including the genetic background of the mice or humans studied, microbiome composition across animal facilities, modified experimental colitis protocols, and differences in NLRP3 ablation methods." (PMID 36199683, 2022). "Other studies reported increased colitis symptoms in Nlrp3-/- mice when compared to WT mice." (PMID 35911682, 2022). "Previous reports have demonstrated that ROS is an important regulator of the NLRP3 inflammasome, thus the anti-colitis and anti-inflammasome effects of CA may exert via down-regulating ROS." (PMID 36090968, 2022). "Previous studies have shown that the levels of TNF-α and IL-1β decreased in the NLRP3−/−mice with colitis, indicating that NLRP3 could regulate the release of inflammatory cytokines." (PMID 35745163, 2022). "In line with previous studies showing a role for NLRP3 inflammasome in DSS colitis etiopathogenesis, we found an increased expression of both IL1B mRNA and inflammasome components, as well as protein levels of pro-Caspase-1, in colonic tissue of DSS-treated mice." (PMID 35327334, 2022). "ER stress responses activate proinflammatory pathways and previous studies have linked ER stress as a cause for DSS-induced colitis in vivo specifically, and in the pathophysiology of IBD in general, both of which also share a strong correlation with NLRP3 inflammasome activation." (PMID 35246034, 2022). "Interestingly, different studies investigating the role of the NLRP3/CASP1 pathway in mice with DSS-induced colitis are either in line with our findings or report the complete opposite." (PMID 35911682, 2022). "Indeed, the release of IL-1β is driven by the activated NOD-like receptor family pyrin domain containing 3 (NLRP3) inflammasome, which is harmful in colitis." (PMID 36145301, 2022). "The results indicated that electroacupuncture may ameliorate colitis by suppressing the NLRP3/IL-1β pathway." (PMID 35075366, 2022). "It is recently found that 10-hydroxy-2-decenoic acid (10-HDA), the most abundant fatty acid and major lipid component in royal jelly, alleviated DSS-induced colitis and enhancing colonic barrier function by regulating the NLRP3/caspase-1/GSDMD-mediated pyroptotic pathway." (PMID 36505474, 2022). "The monitoring of NLRP3 inflammasome protein levels in the inflamed colon tissue of Kunming mice (colitis model), by Western blot analysis, after sinapic acid treatment for 7 days, have shown a reduction in the amounts of NLRP3, ASC, IL-1β, and caspase-1 proteins." (PMID 35276849, 2022). "Other studies have also reported that activating CB2R ameliorates the pathogenesis of experimental autoimmune encephalomyelitis by suppressing the NLRP3 inflammasome and the protective effect of colitis gained via CB2R-mediated inhibition of NLRP3 inflammasome." (PMID 36463179, 2022).
colitis (continued). "Silencing of NLRP3 reversed the anti-inflammatory effect of Forsythia suspensa extract, which indicates that inhibition of pyroptosis is one of the main mechanisms by which Forsythia suspensa extract relieves cell death in colitis." (PMID 35326124, 2022). "By inhibiting the activation of NLRP3 in macrophages, the experimental colitis can be improved." (PMID 35075366, 2022). "However, the protective effect of viable A. muciniphila against DSS-induced colitis was shown to be dependent of NLRP3 activation." (PMID 35874661, 2022). "In general, both overexpression and deletion of Nlrp3 lead to the production of AMPs and changes in gut microbiota, which may be critical for the development of colitis and CRC." (PMID 35954484, 2022). "The discrepancies regarding the role of NLRP3 inflammasome in colitis may be explained by environmental factors including microbiota and diet." (PMID 35722277, 2022). "Curcumin and procyanidin could alleviate DSS-induced colitis through inhibiting NLRP3 inflammasome activation." (PMID 34299310, 2021). "It was found that the inhibition of NF-κΒ and NLRP3 inflammasome in macrophages could ameliorate colitis of mice." (PMID 34439523, 2021). "Thus, colitis induced NLRP3-dependent Aβ accumulation in the cortex and hippocampus, possibly by suppressing glymphatic clearance, consistent with the observed neuropathology, neuroinflammation, and impaired spatial cognition." (PMID 34229722, 2021). "Moreover, administration of the NLRP3 inhibitor, MCC950, ameliorated the intensified colitis in IRGM-deficient mice." (PMID 33808793, 2021). "Additionally, AMPK can suppress the activation of NLRP3 inflammasome by decreasing NF-κB activation, thereby attenuating colitis." (PMID 34628369, 2021). "This study suggested that regulation of the NLRP3 inflammasome activation might be critical to phloretin’s capacity to reduce colitis." (PMID 33808793, 2021). "Thus, Schisandrin B induced AMPK/Nrf2 signaling pathway to suppress NLRP3 inflammasome in model of colitis by the inhibition of ROS-induced mitochondrial damage." (PMID 34628369, 2021). "Additionally, Ox-LDL/CD36/ ROS generation/TXNIP upregulation/NLRP3 inflammasome activation axis warrants investigation during the course of colitis." (PMID 33917884, 2021). "Moreover, oral administration of the Jmjd3 inhibitor ameliorated the severity of DSS-induced colitis in mice and inhibited the activation of NLRP3 inflammasome in the colon." (PMID 33808793, 2021). "Moreover, results of western blot had further verified that SK can relieve the colitis in mice by inhibiting the activation of NF-κB and NLRP3 inflammasome and disruption of epithelial TJ proteins." (PMID 33505807, 2021). "CR dose-dependently down-regulated Nlrp3, IL-1β, IL-6, Tnf-α and Ccl2 mRNA levels in colitis mice." (PMID 34393786, 2021). "We found that Schisandrin B suppressed NLRP3 inflammasone in vivo and vitro model of colitis." (PMID 34628369, 2021). "Thus, IRGM-deficient mice showed increased NLRP3 inflammasome activation in the colon and increased DSS-induced colitis." (PMID 33808793, 2021). "The NLRP3 inflammasome has a proinflammatory effect during the onset of colitis." (PMID 34408782, 2021). "Thus, the role of EVO in colitis and its impact on NLRP3 inflammasome activation needs to be further studied." (PMID 33808793, 2021). "Also, the NLRP3 inflammasome is a crucial component in the pathogenesis of dextran sulfate sodium (DSS)-induced colitis." (PMID 34443594, 2021). "Their data showed that oral administration of CAI reduced colon disease severity in TNBS-colitis and this reduction was accompanied by reduced activation of NF-kB, as well as reduced activation of the NLRP3 inflammasome and production of pro-inflammatory cytokines in the inflamed colon." (PMID 33808793, 2021).
colitis (continued). "Studies have also shown that the nucleotide-binding oligomerization domain, leucine-rich repeat and pyrin domain-containing 3 (NLRP3) inflammasome is an important signal transduction pathway of colitis injury, playing an important role in regulating cell proliferation, differentiation and apoptosis." (PMID 34628369, 2021). "Thus, we treated TNBS-induced experimental colitis with HPM to investigate the molecular mechanism by which HPM regulates the colonic NLRP3 inflammasome by observing the ATP content and the expression of P2X7R, Pannexin-1 and NF-κBp65." (PMID 34043726, 2021). "CPT-11 could activate inflammasome NLRP3, promote caspase-1 to cleaved the precursor of IL-1β and release a large amount of mature IL-1β into colonic tissue, resulting in colitis." (PMID 34025639, 2021). "A novel tetrahydroquinoline inhibitor of NLRP3, compound 6, specifically inhibits NLRP3 activation in vivo and attenuates colitis severity in the DSS mouse model by directly binding to the NACHT domain of NLRP3, inhibiting its ATPase activity and blocking ASC oligomerization." (PMID 34064909, 2021). "Furthermore, NLRP3 protein expression in colon tissue of DSS induced colitis mice model was induced." (PMID 34628369, 2021). "In contrast with these findings, another study reported that the NLRP3 inflammasome is a critical regulator of intestinal inflammation in the DSS colitis model, and Nlrp3-/- mice develop less severe colitis than wild-type mice and produce lower levels of pro-inflammatory cytokines in colonic tissue." (PMID 34064909, 2021). "A microRNA mimic was used to verify the role of miR-378a-5p/NLRP3 axis in the colitis repair." (PMID 34294138, 2021). "Interestingly, administration of the small molecule andrographolide (Andro), a natural compound, prevents tumorigenesis in a colitis-associated CRC model by inducing mitophagy, which results in NLRP3 inflammasome inhibition." (PMID 34064909, 2021). "The reduced neuropathology observed in NLRP3 KO mice following DSS-induced colitis may have resulted from lower mature IL-1β production and ensuing infiltration of fewer gut-derived T cells." (PMID 34229722, 2021). "In addition, the induction of PTEN-induced putative kinase 1 (PINK1)/Parkin-driven autophagy was shown to protect against DSS-induced colitis through the inactivation of the NLR family pyrin domain containing 3 (NLRP3) inflammasome in macrophages." (PMID 34899362, 2021). "Likewise, mice carrying the same activating mutation (Nlrp3R258W) that is responsible for increased NLRP3 activation and IL-1β levels in patients with cryoporin associated periodic syndrome (CAPS) were resistant to DSS colitis and T cell transfer colitis." (PMID 34344313, 2021). "Moreover, NLRP3 inflammasome-derived IL-1β and IL-18 play a protective role against oxazolone-induced colitis, and a hyperactive NLRP3 inflammasome (such as that in the Nlrp3 R258W mutant mouse line) confers strong resistance to experimental colitis/CRC." (PMID 34064909, 2021). "Walnut oil, which has become a dietary supplement, could alleviate DSS-induced colitis by decreasing the ROS production, inhibiting NLRP3 inflammasome activation, and regulating the composition, relative abundance and SCFAs levels of gut microbiota." (PMID 34299310, 2021). "Thus, our findings showed that NLRP3 inflammasone, a target spot of Schisandrin B on colitis to reduce inflammation factor of intestinal epithelial cells." (PMID 34628369, 2021). "Thus, we conclude that Schisandrin B suppressed NLRP3 inflammasome activation-mediated IL-1β level and pyroptosis in intestinal epithelial cells of colitis model by the activation of AMPK/Nrf2 dependent signaling- ROS-induced mitochondrial damage." (PMID 34628369, 2021). "There have been many studies of the correlation between NLRP3 and colitis." (PMID 34612661, 2021). "Similarly, NLRP3 is protective in the oxazolone model of colitis, and disease severity can be ameliorated by exogenous administration of IL1β or IL1862." (PMID 34075172, 2021).
colitis (continued). "However, LYVE-1 staining indicated that meningeal lymphatic endothelial cells were unaffected by colitis or NLRP3 depletion." (PMID 34229722, 2021). "Then, in in vivo experiments, they showed that the intensified colitis could be ameliorated by depletion of CCR2+ inflammatory monocytes, and that overexpression of miR-223 caused blockade of IL-1β or NLRP3." (PMID 33808793, 2021). "In summary, our in vivo and in vitro studies showed that Xi Lei San could significantly relieve the symptoms of colitis in DSS-induced colitis model rats by suppressing the activity of NLRP3 inflammasomes and reducing autophagy." (PMID 33967625, 2021). "QYSXD may ameliorate colitis by inhibiting the expression of RIP1/RIP3/NLRP3 pathway-related proteins and reversing mitochondrial dysfunction to control inflammation." (PMID 34462641, 2021). "At the same time, Schisandrin B not only reduced inflammation in vivo and vitro model of colitis, but also suppressed the nucleotide-binding oligomerization domain, leucine-rich repeat and pyrin domain-containing 3 (NLRP3) inflammasome in vivo and vitro model of colitis." (PMID 34628369, 2021). "Our results confirmed that lactic acid-producing S. cerevisiae not only suppressed M1 macrophage polarization but also inhibited NLRP3 inflammasome, which indicated that lactic acid-producing S. cerevisiae may exert this synergistic effect in colitis." (PMID 34899735, 2021). "TLR4/NLRP3 plays key roles in regulating intestinal homeostasis, maintaining intestinal epithelial barrier integrity, and reducing mortality during experimental colitis and can also affect the composition of the intestinal biota." (PMID 33505499, 2021). "Inhibiting excessive NLRP3 activation can alleviate the inflammatory response in the colitis." (PMID 34899735, 2021). "Taken together, the protective effect of OCOP against DSS-induced colitis might be intimately related to inhibition of NF-κB pathway and NLRP3 inflammasome." (PMID 33859564, 2021). "There are reports that treatment with NLRP3 inhibitors can relieve colitis under DSS exposure, which might be caused by the local reduction of pro-inflammatory cytokines, including IL-1β, TNF-α, and IFN-γ." (PMID 34955826, 2021). "NLRP3 activation involved in the protective effect of A. muciniphila on colitis." (PMID 34612661, 2021). "This review will discuss the role of nuclear receptors in the control of the NLRP3 inflammasome and the putative beneficial effect of new modulators of inflammasomes in the treatment of inflammatory diseases including colitis, fulminant hepatitis, cardiac ischemia–reperfusion and brain diseases." (PMID 33716981, 2021). "Colitis can exacerbate age-related neuropathology, while suppression of NLRP3 inflammasome activity may protect against these deleterious effects of colitis." (PMID 34229722, 2021). "Cinnamaldehyde (CA) is a main active ingredient of cinnamon and CA could alleviate dextran sulfate sodium (DSS)-induced colitis by inhibiting activation of NLRP3 inflammasome." (PMID 34055024, 2021). "Conversely, many reports are suggesting that the microbiota activate NLRP3 and exacerbate colitis." (PMID 33917884, 2021). "To clarify whether the protective effect of A. muciniphila in colitis depends on NLRP3, we performed the NLRP3-deficent assay." (PMID 34612661, 2021). "Several studies have revealed that NLRP3 inflammasome, a key sensor in the pyroptosis signaling pathway, could be activated in the colitis model." (PMID 34828992, 2021). "A. muciniphila abundance correlates with the expression of NLRP3 in colitis." (PMID 34612661, 2021). "Next, we investigated whether administration of these compounds affected NLRP3 inflammasome activation in the experimental colitis model." (PMID 33350984, 2021). "However, it has also been found that the IL-1β and IL-18 produced by NLRP3 inflammatory complexes have protective effects against colitis, although the mechanism is still unclear." (PMID 34462641, 2021).